FBLN5 (fibulin 5)
Diseases named in the same sentence as FBLN5 in open-access papers (continued):
Sharing a sentence is not in itself a finding about the gene and the disease.
cancer (continued). "We further explored whether FBLN5 could also be used as a prognostic indicator in other cancers using a combination of the expression levels of FBLN5 in various cancer types and their prognosis." (PMID 36672502, 2023). "Abnormal FBLN5 expression levels are related to various cancer types." (PMID 36672502, 2023). "As FBLN5 is an extracellular matrix protein derived from fibroblasts, we suspect that FBLN5 also inhibited the activity of immune cells and allowed for the immune escape of cancer cells to occur." (PMID 36672502, 2023). "Long-term F. nucleatum stimulation may increase the risk of cell carcinogenesis by altering many inflammation- and cancer-related genes and pathways, such as Mnda, Cyp1b1, Comp, Phex, Mmp3, Tnfrsf1b, Fbln5, and Nfkb2." (PMID 33042984, 2020). "Fibulin-5 mRNA expression is downregulated in the majority of human tumors, particularly in metastatic malignancies of the kidney, breast, ovary, and colon, suggesting its inhibitory role in advanced cancer development." (PMID 30227601, 2018). "The effects of fibulin-5 on cancer development are complex and warrant further investigations." (PMID 30227601, 2018). "Nevertheless, this in vitro experiment suggests that FBLN5 may protect EOC metastasis by preventing cancer cell adhesion to specific ECM proteins." (PMID 29581841, 2018). "Additionally, injection of cell lines modified to overexpress Fbln5 into mice resulted in fewer metastatic deposits than unaltered cancer cell lines." (PMID 29581841, 2018). "Interestingly, FBLN5 also prevent these cells from forming mammospheres, a key feature of cancer stem cells." (PMID 27941907, 2016). "Finally, we showed that FBLN5 degradation may play an important pathologic role in EOC because full length FBLN5 inhibited cancer cell adhesion to select basement membrane proteins laminin and type I collagen." (PMID 29581841, 2018). "We hypothesize that the reason NAFs also secrete fibulin-5 and promote cell migration and invasion is that normal fibroblasts may become activated in the adjacent normal tissue surrounding tumors by cytokines, or activated fibroblasts may be recruited from cancers." (PMID 40369121, 2025). "Single-cell analysis showed that FBLN5 and LAD1 were overexpressed in fibroblasts and cancer cells, respectively, compared to normal cells." (PMID 37325048, 2023). "However, a limitation of this study is the inability to identify the exact mechanism by which fibulin-5 activates the CREB–GSK-3αβ pathway, ultimately resulting in cancer progression through EMT enhancement in DGC." (PMID 40369121, 2025). "FBLN5 was notably upregulated in fibroblasts, and LAD1 was markedly upregulated in cancer cells." (PMID 37325048, 2023). "Culture media recovered from EOC cell lines treated with vehicle (Ctl) or TGFβ1 (5 μg/ml) for 48 h did not proteolyze FBLN5, and cancer cell extracts did not metabolize FBLN5." (PMID 29581841, 2018). "Activation of the Wnt pathway due to fibulin-5 silencing may help drive epithelial-mesenchymal transition (EMT), a critical event in cancer metastasis, which is known to involve aberrant Wnt signaling, ERK signaling, and MMP activation." (PMID 25909283, 2015).
infection (4 papers, 2017 to 2025). The state of being infected such as from the introduction of a foreign agent such as serum, vaccine, antigenic substance or organism. "EFEMP1 and LTBP4 were additionally downregulated at 12 hpi and 24 hpi following Delta infection, while EGFL6 and FBLN5 showed consistent downregulation at both time points in Omicron infection." (PMID 41200555, 2025). "Following adenovirus-mediated infection of Ad-Fbln5 in INS-1 cells, overexpression of Fbln5 was confirmed by measuring the mRNA and protein expression levels." (PMID 28539593, 2017).
adenocarcinoma (1 paper, 2023). A common cancer characterized by the presence of malignant glandular cells. "FBLN5 was expressed at low levels in the cytoplasm of poorly differentiated adenocarcinoma cells and highly expressed in interstitial fiber cells." (PMID 36672502, 2023).
FBLN5 also shares sentences with these, for which no sentence is quoted: lung adenocarcinoma (3 papers); prostate carcinoma (3); age-related macular degeneration 3 (2); liver cancer (2); nasopharyngeal carcinoma (2); acute myeloid leukemia (1); benign ovarian cystadenomas (1); biliary atresia (1); cardiac disease (1); cardiovascular diseases (1); cerebral artery diseases (1); cerebral atherosclerosis (1); cerebrovascular diseases (1); chronic hepatitis (1); coronary heart disease (1); diabetic neuropathy (1); diastolic heart failure (1); Ehlers-Danlos syndrome (1); epithelioid angiosarcoma (1); epithelioid hemangioma (1); gingivitis (1); glioblastoma (1); Granuloma (1); hemorrhage (1); hepatitis C (1); Hernia (1); hypercoagulable (1); hypertriglyceridemia (1); Inguinal hernia (1); intracerebral hemorrhage (1).
A further 20 diseases each share a sentence with FBLN5 in 1 paper.